KLK2 (kallikrein related peptidase 2)
Diseases named in the same sentence as KLK2 in open-access papers (continued):
Sharing a sentence is not in itself a finding about the gene and the disease.
prostate carcinoma (continued). "Since prostate cancer (PCa) is the second most common cancer in men with 1.4 million new cases and 400,000 deaths every year, predominantly KLK3/PSA and to a lesser extent KLK2 have become diagnostic tools and drug targets." (PMID 41516101, 2025). "T cell engagers based on KLK2 are currently in early clinical development in prostate cancer." (PMID 38396898, 2024). "In addition, a reduction in SMARCA4-related target genes, including the protein KLK2, a known prostate cancer apoptosis inhibitor, was found in SMARCA4-deficient prostate cancer cells." (PMID 39697230, 2024). "Additionally, a study of prostate cancer cells with inhibited BRG1 found that several of BRG1’s target genes were decreased, including protein KLK2, a known apoptosis inhibitor in prostate cancer." (PMID 36769189, 2023). "Therefore, KLK2 has been used in many studies as a biological prostate cancer prognosis marker as well as a therapeutic target." (PMID 37232542, 2023). "Moreover, KLK2 has been found to enhance the proliferation of prostate cancer castration-resistant cells through protease-activated receptors (PAR)." (PMID 37593117, 2023). "Compared with PCA3 and epiCaPture, UCA1 scores normalized to KLK2 may result in better performance in prostate cancer patients." (PMID 35289508, 2022). "Liquid biopsy of exosomes isolated from patients with prostate cancer revealed that exosomes are enriched for genes that are hallmarks of prostate cancer, such as androgen receptor, kallikreins (KLK2), cyclin-dependent kinase inhibitor 1A (CDKN1A), KLK10, JUN, and B2M (β2 microglobulin)." (PMID 36726968, 2022). "KLK2 is another enzyme (previously named human kallikrein 2, hK2) that may be used for targeting drugs toward prostate cancers." (PMID 33673582, 2021). "In contrast, low expression of KLK2 was associated with advanced tumour stage, more lymph node metastasis, increased cell proliferation, positive resection margin, and early PSA recurrence in prostate cancer." (PMID 34552064, 2021). "Notably, the “prostate cancer” pathway comprises KLK2, the most strongly downregulated DEGSD (log2 fold-change −12.6)." (PMID 34768937, 2021). "Similar to KLK3, also Kallikrein related peptidase 2 (KLK2) functions in hydrolyzing seminogelins and is regulated by androgen receptor, upregulated in prostate tumor cells, and recognized as potential prognostic maker for prostate cancer risk." (PMID 33114768, 2020). "The transgenic cancer susceptible mouse with prostate specific expression of human hK2 (Hi-Myc x pb_KLK2) recapitulates the biology of human prostate cancer and was engineered to investigate the radiobiological mechanisms that are the design foundation for [225Ac]hu11B6." (PMID 29691406, 2018). "Alternative protein cleavage and glycosylation of KLK2 may correlate with the disease state, suggesting that KLK2 monitoring may increase the sensitivity and specificity of prostate cancer markers." (PMID 26582203, 2016). "Notably, one group of genes with very strong negative correlations (≤-0.9) to radiomic features were found to be associated with the AR signaling genes: KLK2, KLK3, HOMER2, BMPR1B, or belong to validated prostate cancer classifiers: CHRNA2, MT1H, DPP4, MYBPC1." (PMID 27438142, 2016). "In prostate carcinoma, KLK2 may promote growth or metastasis of tumor cells by interacting with the urokinase-type plasminogen activator system." (PMID 25326387, 2014). "As both KLK3 and KLK2 genes are regulated by AR signalling, it is reasonable to theorize that the 11B6 antibody could be used to image AR signalling in prostate cancer in a similar fashion to that reported with 5A10." (PMID 26116115, 2014). "KLK2 protein (hK2), is also considered as a secondary marker of prostate cancer." (PMID 23587030, 2013).
prostate carcinoma (continued). "While it is difficult to make direct comparisons between this study and others that used LCM to examine altered expression in tumor vs. normal epithelia, we and others observed genes elevated in prostate cancer epithelial cells including kallikrein proteins 2 (KLK2), and 3 (KLK3, or PSA)." (PMID 20426842, 2010). "KLK2 may therefore represent a novel therapeutic target as well as a biomarker for prostate cancer." (PMID 39272956, 2024). "Similarly to PSA, KLK2 is also secreted from the prostate and prostate cancer cells." (PMID 33673582, 2021). "Hence, elevated KLK2 levels in blood may constitute a valid marker for prostate cancer either alone or in combination with levels of various KLK3 isoforms." (PMID 25326387, 2014). "In contrast to the expression of well-established prostate cancer targets (PSMA, PSCA, and STEAP1), KLK2 expression is highly prostate-specific." (PMID 40627156, 2025). "In conclusion, KLK2, KLK3, KLK4, KLK5, KLK11, and possibly KLK15 are important for normal prostate physiology but become reprogrammed in prostate cancer to drive tumor progression." (PMID 41516101, 2025). "Using public genomic information, we observed a mild correlation between KLK2 expression levels and the viability of VCAP (RRID:CVCL_2235) and LNCAP-CLONE-FGC (RRID:CVCL_1379), two prostate cancer cell lines." (PMID 38396898, 2024). "Genes regulated by AR, such as KLK2, NKX3.1, and KLK3 (PSA), are extensively studied in prostate cancer." (PMID 38791417, 2024). "Other targets of interest include the PSCA (NCT05732948 and NCT05805371) and kallikrein 2 (KLK2) (NCT05022849), both of which display high expression in prostate cancer." (PMID 37762648, 2023). "We found that the prostate cancer-specific genes, including KLK3, KLK2, FOLH1, and ACPP, are expressed mainly in luminal cells." (PMID 36712886, 2022). "It is noteworthy that KLK2 featured recurring significantly in our assessment: it is the most strongly downregulated DEGSD, a member of the “prostate cancer” pathway, a putative prostate-specific marker and it is involved in the hormonal axis of PCa." (PMID 34768937, 2021). "Specifically, half of the “prostate cancer” pathway DEGsSD had previously been referred to in the literature (AR, CDKN1A, CTNNB1, EGFR, KLK2, NKX3-1, PDGFRA, SRD5A2)." (PMID 34768937, 2021). "Our results point to the fact that KLK1, KLK2, and KLK14 (only in recurrent prostate cancer tissues) are underexpressed in prostate cancer tissues, while KLK3, KLK4, KLK8, and KLK9 are overexpressed in both recurrent and non-recurrent tissues." (PMID 33150763, 2020). "The related kallikrein gene KLK2 had expression that was highly correlated with KLK3, as did TMPRSS2, one of the genes involved in the TMPRSS2:ERG translocation that is common in prostate cancer." (PMID 33303959, 2020). "We performed knockdown studies in prostate cancer cells using siRNA against all three factors (siOSN) and confirmed downregulation of the cardinal biomarkers of prostate cancer progression (PSA and KLK2) in FM." (PMID 30742096, 2019). "As expected, prostate-specific KLKs (KLK2 and KLK3) were expressed only in the prostate cancer (LNCaP) cell line." (PMID 28414719, 2017). "Human kallikrein-related peptidase 2 (KLK2) is a key serine protease in semen liquefaction and prostate cancer together with KLK3/prostate-specific antigen." (PMID 26582203, 2016). "Other genes identified as highly enriched in prostate cancer were TGM4, KLK2 and KLK4, the latter kalekrein-related proteins belonging to the same family as PSA (KLK3)." (PMID 26237329, 2015). "We analyzed 14 additional genes, including the AR-activated genes PSA, FKBP51, ORM1, STAG, Nkx3.1, FASN, AQP3, KLK2, and UGT2B; the AR-repressed genes DKK and FST; and the castration-resistant prostate cancer AR-regulated genes CDC20, CDK1, and UBE2C." (PMID 22761715, 2012).
prostate carcinoma (continued). "For example, KIT in gastrointestinal stromal tumor (GIST; second highest weight in GIST, 0.95) and KLK2 and KLK3 in prostate cancer (the two highest weights in prostate adenocarcinoma, 0.97 and 0.95, respectively)." (PMID 21955394, 2011). "KLK2 and PSA are androgen regulated serine proteases expressed in prostate epithelial cells and upregulated in prostate cancer." (PMID 20426842, 2010). "The ratio of KLK2 to free PSA improves the discrimination of benign prostate hyperplasia and prostate cancer patients." (PMID 19055846, 2008). "Five of these top seven genes namely, MYLK, KLK2, KLK3, LTF and TGM4 had already been specifically related to prostate carcinoma." (PMID 19055846, 2008). "KLK2 × CD3–mediated immune synapse formation was observed by F-actin polarization with KLK2 staining on VCaP cells and CD3 staining on T cells, indicating increased engagement of T cells and prostate cancer cells in the presence of KLK2 × CD3." (PMID 40627156, 2025). "Considering the link between HSPs and AR activity, we next investigated the impact of NXP800 on AR signaling, demonstrating a decrease in AR-FL and AR-V7 protein expression, and also in expression of AR-responsive genes (KLK2, KLK3, TMPRSS2, and FKBP5), across all three prostate cancer cell lines." (PMID 39787247, 2025). "IHC on 9576 prostate cancers noted KLK2 was negative in 23%, weak in 38%, moderate in 35%, and strong in 4% of prostate cancers." (PMID 39272956, 2024). "Previous studies in prostate cancer have also shown that miR-143-3p can inhibit cell growth through various targets, including KRAS, Bcl-2, ERK5, LIMK1, HK2 and KLK2." (PMID 37759434, 2023). "Kallikrein-related peptidase 2 (KLK2) is one of the biomarkers that are highly expressed in prostate cancer but not in normal prostate tissue." (PMID 35163550, 2022). "KLK2 is mainly expressed in PRAD and KIRC, resulting in prostate cancer." (PMID 36016607, 2022). "Furthermore, half of the “prostate cancer” pathway DEGsSD are well described in the PCa literature (AR, CDKN1A, CTNNB1, EGFR, KLK2, NKX3-1, PDGFRA, SRD5A2), confirming that this is a pivotal pathway to specifically target clinical questions on canine PCa." (PMID 34768937, 2021). "Finally, the “prostate cancer” pathway also includes DEGsSD that are relatively specific to the (human) prostate (SRD5A2, KLK2, NKX3-1 and CREB3L4), proto-oncogenes (EGFR, PDGFRA, PDGFRB, NRAS) and druggable candidates (PIK3CD, CTNNB1, PIK3CG, CDKN1A)." (PMID 34768937, 2021). "The “prostate cancer” pathway also comprises genes that are relatively specific to the (human) prostate (CREB3L4, KLK2, NKX3-1 and SRD5A2), proto-oncogenes (EGFR, NRAS, PDGFRA and PDGFRB), and druggable candidates (CDKN1A, CTNNB1, EGFR, NRAS, PDGFRA, PDGFRB, PIK3CD and PIK3CG)." (PMID 34768937, 2021). "In conclusion, we propose that KLK1, KLK2, KLK3 KLK4, KLK8, KLK9, and KLK14, which are differentially expressed in prostate cancer, could be used as promising biomarkers of prostate cancer progression." (PMID 33150763, 2020). "Transcript analysis of additional prototypical AR‐regulated genes FKBP5, KLK2, NKX3.1, and TMPRSS2 shows a similar pattern of expression to PSA and Ki67, indicating general inhibition of androgen signaling by bicalutamide in prostate cancer PDEs." (PMID 30117261, 2018). "Of these, approaches to measure distinct molecular forms of PSA (free, intact, complexed PSA, and pro-PSA) combined with kallikrein-related peptidase 2 (KLK2), also known as hK2, have been considered holding particular promise in enhancing the diagnosis of prostate cancer." (PMID 24809052, 2014). "We also found a fusion between the KLK2 gene and the ETS gene ETV4 in clinical prostate cancer." (PMID 19461893, 2009). "Previous reports showed that KLK2 expression is highly prostate-specific, with little-to-no expression in non-prostatic tissues and that its expression remains relatively homogeneous across disease stages in prostate cancer [Gene Page (cited June 17, 2025)." (PMID 40627156, 2025).
prostate carcinoma (continued). "In prostate cancer, androgen-activated nuclear AR functions as a classical transcription factor with relatively well-characterized transcriptional repertoire, including genes such as PSA, KLK2, FKBP5, and TMPRSS2, the alteration of which promotes prostate tumor aggressiveness." (PMID 38326303, 2024). "In our study, KLK2, KLK3, and KLK4 were identified as gene signatures for prostate cancer; KLK3 is a prostate-specific antigen that is a gold-standard clinical biomarker widely employed in the diagnosis and monitoring of prostate cancer; KLK2 showed promise as prostate cancer biomarker, as well." (PMID 32850691, 2020). "The SNPs identified are mainly in regions that had not previously been known to be associated with prostate cancer risk that might be clinically relevant, such as MYC, MSMB, KLK2 and KLK3 genes." (PMID 27819754, 2017). "The MYLK, KLK2, KLK3, HAN11, LTF, CSRP1 and TGM4 genes presented significant changes in their functional connectivity between normal and tumoral conditions and were also classified as the top seven most informative genes for the prostate cancer genesis process by our discriminant analysis." (PMID 19055846, 2008).
prostate tumor (11 papers, 2008 to 2025). "KLK2 is highly expressed in prostate tumor cells and might be a prognostic marker for PCa risk." (PMID 31500625, 2019). "Using genomic information from different sources, we evaluated the immune microenvironment and genomic profile of prostate tumors with high expression of KLK2." (PMID 38396898, 2024). "In the current work, by using genomic information we evaluated the immune microenvironment and genomic profile of prostate tumors with a high expression of KLK2." (PMID 38396898, 2024). "In the case of prostate tumors with high KLK2 expression, it is unknown how the microenvironment can influence the immune response." (PMID 38396898, 2024). "Of note, the expression of KLK2 in prostate tumors does not associate with a detrimental prognosis (HR = 0.96, p = 0.95)." (PMID 38396898, 2024). "The KLK2 protein product is emerging as a new prostate tumor marker." (PMID 33150763, 2020). "Notably, genes associated with luminal differentiation (i.e. FOXA1, TMPRSS2, HOXB13, KLK3, KLK2) had significantly reduced expression in the ‘low’ NKX3.1 prostate tumors." (PMID 30266798, 2018). "Interestingly, the only evidence, EST (BF372485), in the public database for one of the tumor-specific splice event joining one of the intron in KLK3 gene to an intron in KLK2, is also derived from prostate tumor-tissue." (PMID 23181285, 2012). "To evaluate KLK2 as a potential therapeutic target for T-cell engagers, we developed a bispecific antibody, KLK2 × CD3, which binds to CD3 receptor complexes on T cells and KLK2 on the surface of prostate tumor cells." (PMID 40627156, 2025). "Moreover, among the identified genes we found classically known biomarkers and genes which are closely related to tumoral prostate, such as KLK3 and KLK2 and several other potential ones." (PMID 19055846, 2008). "In addition, seven other genes, GGT1, HDAC1, KLK2, MYO6, PLA2G7, BICD1, and CACNAID, were found to be differentially expressed in prostate tumors of non-BCR and BCR patients." (PMID 31741711, 2019).
prostate adenocarcinoma (10 papers, 2011 to 2025). "A complete biodistribution study of [225Ac]hu11B6 was performed in a genetically modified mouse model (Hi-Myc x pb_KLK2) that has prostate specific expression of human hK2 (pb_KLK2) and spontaneous development of prostate adenocarcinoma (Hi-Myc) at 20–30 weeks of age." (PMID 29691406, 2018). "Interestingly, canonical prostate adenocarcinoma cell-surface targets KLK2 and STEAP1 had significantly lower expression in the LumB versus LumA samples, and STEAP2 also had a trend toward lower expression in LumB, in contrast to FOLH1, which was highly expressed in both luminal CTC phenotypes." (PMID 39912912, 2025). "KLK2 was specifically expressed in prostate adenocarcinoma (PRAD) compared with other solid and hematologic malignancies." (PMID 38396898, 2024). "Prostate adenocarcinoma and urothelial bladder carcinoma exhibited significant up-regulation of KLK2 and KLK4 gene expressions (KLK2: 3-fold and 2-fold, KLK4: 3-fold and 2-fold)." (PMID 29707153, 2018). "Consistent with previous reports, KLK2 expression was restricted to normal prostatic tissues and prostate adenocarcinoma with little-to-no expression outside the prostate." (PMID 40627156, 2025). "In prostate adenocarcinoma (PRAD), the family of KLK genes KLK2, KLK3, and KLK4 are enriched in both the prostate and prostate cancer." (PMID 40453216, 2025).
breast carcinoma (4 papers, 2013 to 2023). "Herein, GSEA revealed that ARGs might be involved in the process of transcription of genes KLK2 and KLK3 in breast cancer, which might offer clues for a more in-depth investigation of ARGs and anoikis resistance in breast cancer." (PMID 37842046, 2023).
chromophobe renal cell carcinoma (1 paper, 2018). Chromophobe renal cell carcinoma is a rare subtype of renal cell carcinoma, originating from the intercalating cells of the collecting ducts and macroscopically manifesting as a well-circumscribed, highly lobulated, solid tumor that is usually diagnosed at an early stage. "Chromophobe renal cell carcinoma also had 4 up-regulated KLKs with excellent diagnostic power (KLK2: 0.990, KLK3: 0.974, KLK4: 0.989, KLK15: 0.97)." (PMID 29707153, 2018). "We identified four viable cancer biomarkers (KLK2, KLK3, KLK4 and KLK15) for chromophobe renal cell carcinoma with almost perfect sensitivity and specificity (AUC values: 0.97–0.99)." (PMID 29707153, 2018). "Chromophobe renal cell carcinoma had increased expression of the following KLKs: KLK1 (32-fold), KLK2 (12-fold), KLK3 (69-fold), KLK4 (234-fold), KLK15 (132-fold), whereas decreased expression of KLK5 (5-fold), KLK6 (13-fold), and KLK7 (26-fold)." (PMID 29707153, 2018). "Our analysis differed and found that KLK1, KLK2, KLK3, KLK4 and KLK15 are highly upregulated in chromophobe renal cell carcinoma." (PMID 29707153, 2018). "Thyroid carcinoma had three KLKs (KLK2: 0.943, KLK4: 0.914, KLK15: 0.905) that had AUC values above 0.90 threshold and KLK7 had an AUC of 0.910 in Chromophobe renal cell carcinoma." (PMID 29707153, 2018).
Infertility (1 paper, 2017). "Among studies on KLK genes, Lee and Lee (2011) genotyped KLK2 SNPs (+255 G > A, rs2664155) in 218 infertility cases and 220 fertile controls and found a significant correlation of the polymorphisms with male infertility." (PMID 28894123, 2017).
intraepithelial neoplasia (1 paper, 2018). A precancerous neoplastic process that affects the squamous, glandular, or transitional cell epithelium without evidence of invasion. "This GEM model shows higher KLK2 expression in the ventral and dorsal lateral prostate lobes than the anterior, which correlates to the commonly observed rate of spontaneous adenocarcinoma development and intraepithelial neoplasia in the respective lobes of a Hi-Myc GEM." (PMID 29691406, 2018).
kidney cancer (1 paper, 2020). Primary or metastatic malignant neoplasm involving the kidney. "We found that LSD1 binds to AR target genes including KLK2, KLK3, and TMPRSS2 in kidney cancer cells, and confirmed that the binding decreased in LSD1 shRNA-expressing cells." (PMID 32847068, 2020).
leukemia (1 paper, 2022). A malignant (clonal) hematologic disorder, involving hematopoietic stem cells and characterized by the presence of primitive or atypical myeloid or lymphoid cells in the bone marrow and the blood. "This difference is mainly found in proteins functionally related to each pathology, for example: sCD44, HIF1A, ZMYM3 or PTPRC for CSF + LM in lymphoma and S100A9, TRAF3, KLK3, KLK2, PTPRC, among others, in the case of CSF + LM in leukemia." (PMID 35053611, 2022).
lung carcinoma (1 paper, 2022). "For instance, promoter regions of Human kallikrein 2(KLK2) in prostate, Apolipoprotein A1 (APOA1) in liver, NK6 homeobox 3 (NKX6.3) in stomach, paired box gene-8 (PAX-8) in kidney, and Surfactant Protein B (SFTPB) in lung cancers were among the selected markers from our pipeline." (PMID 35729208, 2022).